HSPB2 (heat shock protein family B (small) member 2)
Diseases named in the same sentence as HSPB2 in open-access papers (continued):
Sharing a sentence is not in itself a finding about the gene and the disease.
transitional carcinoma (1 paper, 2023). "Initial analyses revealed increased vs. human transitional carcinoma cells, expression levels of the HSPB2 and HSPB3 genes and proteins in high grade BlCa cell lines." (PMID 36768927, 2023).
cancer (11 papers, 2015 to 2025). A tumor composed of atypical neoplastic, often pleomorphic cells that invade other tissues. "Analysis of the CRC data set of TCGA, COAD and READ data set of GEPIA showed that the expression of HSPB2 in cancer tissues was significantly reduced compared with normal tissues." (PMID 35154459, 2022). "By contrast, HSPB2 negatively correlated with cell proliferation in 20 cancer types, and DNAJB2 negatively correlated with cell proliferation in 18 cancer types." (PMID 33225964, 2020). "HSPB2 has been reported to be epigenetically or transcriptionally altered in some human cancers, with potential roles in tumor growth, metastasis, and in particular drug resistance." (PMID 31088577, 2019). "Moreover, compared with normal tissues, the expression of HSPB2 mRNA in cancer tissues was significantly reduced according to the CRC dataset of TCGA, the COAD and READ datasets of GEPIA." (PMID 35154459, 2022). "Previous studies in other cancer cell lines have shown that the CRYAB and HSPB2 double knockout (DKO) can play an important role in inducing cell apoptosis and necrosis." (PMID 36009022, 2022). "Consequently, HSPB2 mRNA expression status could be combined with other well-validated clinical biomarkers, which could tailor the therapeutic options aiming to improve the outcome of cancer therapy and a patient’s overall survival, while minimizing the associated risk." (PMID 36077156, 2022).
tumor (10 papers, 2009 to 2025). "Specifically, we found that BrCa patients with an HSPB2-positive expression status entailed a 2.29-fold higher risk of tumor recurrence as compared to HSPB2-negative ones (HR = 2.29, 95% CI = 1.19–4.42, p = 0.014)." (PMID 36077156, 2022). "When miR-17-5p and HSPB2 expression were increased simultaneously, the reintroducing HSPB2 caused by co-overexpression attenuated the tumor-promoting effect of overexpressed miR-17-5p, as shown by reduced proliferation, migration and invasion." (PMID 35154459, 2022). "The pro-survival role of HSPB2 and HSPB3 in advanced tumor cells was also evident by our finding that HSPB2, HSPB3 genes expression silencing in high grade BlCa cells enhanced doxorubicin toxicity." (PMID 36768927, 2023). "Focusing on superficial tumors (TaT1), decreased HSPB2 and HSPB3 mRNA levels were correlated with a significantly higher risk for disease recurrence following TURBT, independently of tumor stage, grade, EORTC-risk group, and gender." (PMID 36768927, 2023). "HSPB2, a small heat-shock protein, is a prognostic marker in kidney renal papillary cell carcinoma and may support stress tolerance of tumor cells." (PMID 41470046, 2025). "Following LASSO Cox regression analysis, heat shock protein B2 (HSPB2) and acyl-CoA synthetase medium-chain family member 5 (ACSM5) were identified as the most significant genes associated with tumor microenvironment (TME) alterations and Helicobacter pylori infection." (PMID 40519938, 2025). "More precisely, multivariate Cox models confirmed the unfavorable DFS of TaT1 patients under expressing HSPB2 (HR: 3.101; 95% CI: 1.134–8.484; p = 0.027) or HSPB3 (HR: 4.872; 95% CI: 1.322–17.96; p = 0.017), independently to tumor stage, grade, patient’s age and EORTC risk stratification." (PMID 36768927, 2023). "Consequently, high HSPB2 mRNA expression levels represent an independent prognostic indicator for tumor recurrence in BrCa patients." (PMID 36077156, 2022). "This is the first demonstration of miR-17-5p as a tumor miR targeting HSPB2 in CRC." (PMID 35154459, 2022). "In the rescue experiment, the tumor suppressive effect of HSPB2 was detected and miR-17-5p could promote cell proliferation, migration and invasion by targeting HSPB2." (PMID 35154459, 2022). "Consequently, the role of HSPB2 and HSPB3 in tumor progression could be associated with suppression of malignant cells spontaneous apoptosis." (PMID 36768927, 2023). "Conversely, only four of the thirteen deletions that resulted in a significant decrease in expression in tumors were previously identified as down-regulated when comparing normal and tumor tissue (CRYAB, SACS, HSPB7, and HSPB2)." (PMID 38816397, 2024). "Firstly, the expression levels of HSPB2 and HSPB3 genes were examined in BlCa cell lines of gradually increasing malignancy in order to evaluate their expression according to tumor grade." (PMID 36768927, 2023). "Both HSPB2 and HSPB3 gene expression levels were upregulated in the advanced tumor grade cell line TCCSUP." (PMID 36768927, 2023). "In summary, this study unravels a novel mechanism for tumor progression through which miR-17-5p promotes CRC cell proliferation, migration and invasion by targeting HSPB2." (PMID 35154459, 2022). "HSP-Clust II presents significantly higher levels of some HSPB genes such as HSPB2, HSPB3, CRYAA and CRYAB compared to the others HSP subtypes (a pattern that was also observed in Basal-like tumours)." (PMID 29954368, 2018). "HSPB2 and HSPB3 gene expression levels were upregulated in advanced tumor grade cell lines." (PMID 36768927, 2023). "However, expression levels of DNAJB1 (p = 0.018), HSPB2 (p < 0.001), HSPB6 (p < 0.001) and HSPA1A (p = 0.021) were significantly lower in tumor tissues." (PMID 31222140, 2019).
myopathies (3 papers, 2015 to 2020). "While its role in cataracts and myopathies is well established, αB-crystallin and HspB2 may also play a pathogenic role in other diseases." (PMID 27330996, 2016). "A genetic knockout (KO) mouse model exists deleting both αB-crystallin and HspB2 genes; these mice develop a progressive myopathy as they age." (PMID 27330996, 2016). "The HSPB3 loss-of-function mutation excludes HSPB2-HSPB3 complex formation and causes aberrant HSPB2 phase separation that likely contributes to the myopathy." (PMID 32253739, 2020).
neurodegenerative disease (2 papers, 2012 to 2015). A disorder of the central nervous system characterized by gradual and progressive loss of neural tissue and neurologic function. "Thus, the present finding of prevention of amyloid fibril formation of alpha-synuclein by MKBP/HspB2 has physiological significance in neurodegenerative diseases." (PMID 22272249, 2012).
infection (1 paper, 2025). The state of being infected such as from the introduction of a foreign agent such as serum, vaccine, antigenic substance or organism. "In this study, we first observed elevated expression levels of ACSM5 and HSPB2 in Helicobacter pylori-positive GC patients compared to those without the infection." (PMID 40519938, 2025).
HSPB2 also shares sentences with these, for which no sentence is quoted: esophageal squamous cell carcinoma (2 papers); Bladder Cancer (1); breast adenocarcinoma (1); channelopathies (1); distal hereditary motor neuropathy (1); heart failure (1); Impaired glucose tolerance (1); injury (1); lentivirus infection (1); metastasis (1); retinal degeneration (1); type 2 diabetes (1).